NLRP3 (NLR family pyrin domain containing 3)
Diseases named in the same sentence as NLRP3 in open-access papers (continued):
Sharing a sentence is not in itself a finding about the gene and the disease.
neuropathic pain (16 papers, 2017 to 2025). Chronic pain caused by damage to nerve fibers. "In neuropathic pain, microglia undergo pyroptosis through the activation of the NLRP3 inflammasome, which triggers the release of pro-inflammatory cytokines, thereby exacerbating hyperalgesia." (PMID 40552323, 2025). "This difference in the anti-allodynic effect between GAS and MCC950 suggests that mechanisms other than NLRP3 inflammasome activation can be involved in the occurrence or maintenance of SNL-induced neuropathic pain." (PMID 38835032, 2024). "Studies have shown that the expression levels of NLRP3 and IL-1β are elevated in several rodent neuropathic pain models." (PMID 36361825, 2022). "According to previous reports, NLRP3 was also found to be localized in neurons of SDH in a chronic constriction injury-induced neuropathic pain model and another cancer-induced bone pain model, which was consistent with our result." (PMID 35387668, 2022). "Given that neuropathic pain has a variety of causes and underlying mechanisms and GAS has multiple therapeutic effects in the nervous system, inhibition of NLRP3 inflammasome with GAS could be a useful strategy for treatment of neuropathic pain." (PMID 38835032, 2024). "Based on the fact that miR-23a/CXCR4 regulates neuropathic pain by directly targeting TXNIP and TXNIP regulates the expression of NLRP3 inflammasome in neuropathic pain, we supposed to investigate whether miR-23a or CXCR4 could regulate NLRP3 inflammasome via TXNIP." (PMID 29386025, 2018). "All the compounds also had anxiolytic and antidepressant actions, normalized the up-regulation of the NLRP3 inflammasome, and enhanced/normalized the Nrf2, HO-1, and SOD-1 levels in the DRG and AMG of mice with neuropathic pain." (PMID 37891937, 2023). "We further found that CKO of neuronal FcγRI in the DRG or Syk inhibition can attenuate CCI‐induced Syk activation and NF‐κB p65 activation in DRG neurons and decrease NLRP3, IL‐1β, and IL‐18 expression levels in DRG after neuropathic pain." (PMID 36727833, 2023). "The inhibition of KV1.3 with PAP-1 reduced hyperalgesia, M1 polarization, and the expression of NLRP3, caspase-1, and IL-1β, suggesting that KV1.3 channels may play a key role in neuropathic pain by promoting M1 microglial polarization and activating the NLRP3 inflammasome." (PMID 40566541, 2025).
acute liver failure (15 papers, 2020 to 2024). Rapid deterioration of liver function causing encephalopathy and coagulopathy. "In patients with HBV-associated acute liver failure, hepatic transcript levels of FXR were decreased and the levels of NLRP3 were increased compared with normal." (PMID 38172440, 2024). "HDAC6 regulates the activation of M1 macrophages by downregulating NLRP3 expression during acute liver failure." (PMID 35910382, 2022). "In a mouse model of acute liver failure induced by D-galactosamine, the injection of mouse BM-MSCs significantly reduced the expression of the NLRP3 inflammasome protein and the production of pro-inflammatory cytokines associated with the progression of pyroptosis, IL-1β, and IL-18." (PMID 37894893, 2023). "PGC-1α may induce Nrf2 levels, and then inhibit the NLRP3 inflammasome to protect LPS/D-galactosamine-induced acute liver failure." (PMID 37020714, 2023). "Indeed, previous studies have reported that MSC-EVs therapy for acute liver failure (ALF) through reduction of NLRP3 inflammasome." (PMID 32884023, 2020). "It has been reported that nucleotide‐binding and oligomerization domain‐like receptor (NLR) family pyrin domain containing 3(NLRP3), caspase‐1, and gasdermin D (GSDMD) are activated in D‐galactosamine/lipopolysaccharide (D‐gal/LPS)‐induced acute liver failure." (PMID 35184410, 2022). "Autophagy was activated by rapamycin (4 mg/kg) in an acute liver failure (ALF) mouse model, which was used to further study the expression of Irgm1, NLRP3 inflammasome, autophagy-related proteins, and inflammatory cytokines using both qRT-PCR and Western blot analyses." (PMID 38849356, 2024).
enteritis (15 papers, 2020 to 2025). Inflammation of the small intestine. "We previously reported associations between intestinal inflammation and the NLRP3 inflammasome, suggesting that the development of NLRP3-targeted therapeutics may hold promise in mitigating enteritis during MTX chemotherapy." (PMID 38835771, 2024). "Additionally, the gastrointestinal tract’s role in systemic homeostasis, especially in relation to factors like malnutrition and impaired mucosal barrier function contributing to diseases such as enteritis, underlines the importance of regulatory components like NLRP3 inflammasomes." (PMID 38162646, 2023). "Alternatively, intestinal epithelial cell-mediated SCFAs binds to the G protein-coupled receptor (GPR43) and activates the inflammasome-activating protein NLRP3, inducing the release of IL-18, which has a protective effect on enteritis." (PMID 38596637, 2024). "Another experiment found that s_Lactobacillus johnsonii pretreatment inhibited the activation of the NLRP3 inflammasome and NF-κB signalling in a Salmonella infantis-induced enteritis model." (PMID 35958910, 2022). "It is well known that the MAPK pathway is also vital for the activation of NLRP3 inflammasome and the occurrence of enteritis." (PMID 35051006, 2022). "Luteolin has high anti-inflammatory activity and can effectively inhibit the expression of NLRP3 by inhibiting IL-17A signal in enteritis tissue." (PMID 33149752, 2020). "Reg3b can counteract Salmonella enteritis, and the decreased level of Reg3b in the K-DH group indicates that upregulation of Nlrp3-Reg3b may be an adaptive protective mechanism against the pathogenic risk of Salmonella contamination in DH." (PMID 38756775, 2024). "However, some studies have also shown that in the enteritis model, activation of NLRP3 inflammasome has a protective effect on enteritis, and it has also been found that NLRP3 inflammasome can also inhibit the occurrence of enteritis-related tumors." (PMID 35292015, 2022). "Among these small molecules that inhibit the inflammasome signaling pathway, MNS has previously been reported to promote wound healing by inhibiting the activation of the NLRP3 inflammasome and inhibiting the platelet Glycoprotein IIb/IIIa activation with the classical enteritis drug sulfasalazine." (PMID 35784693, 2022). "Notably, inhibiting NLRP3 inflammatory bodies has been shown to prevent the onset of enteritis." (PMID 38835771, 2024). "It has been established that L. johnsonii L531 could alleviate Salmonella infantis-associated enteritis and promote intestinal secretory IgA production via regulation of NLRC4 and NLRP3 inflammasomes, NF-κB signaling pathway activation and suppression of mitochondrial damage." (PMID 39619663, 2024). "Previous studies have demonstrated that DH can lead to intestinal disorders, enteritis, and an up-regulation of NOD-like receptor protein 3 (NLRP3)." (PMID 38756775, 2024). "In this study, we provide evidence that CAPE facilitates NLRP3 ubiquitination by inhibiting ROS in THP-1 cells and inhibits enteritis and tumor burden by inhibiting NLRP3 in an AOM/DSS mouse model." (PMID 32435622, 2020). "This study is the first description of using compound-MNS on enteritis mice with DSS-induced intestinal inflammation and explored its inhibitory effects on the NLRP3 inflammasome, which may function as an effective therapeutic for IBD." (PMID 35784693, 2022).
ischemia reperfusion injury (15 papers, 2014 to 2025). Adverse functional, metabolic, or structural changes in ischemic tissues resulting from the restoration of blood flow to the tissue (reperfusion), including swelling; hemorrhage; necrosis; and damage from free radicals. "In the case of ischemia-reperfusion injury as an example, mouse cardiac fibroblasts upregulate Nlrp3 and trigger the release of IL-1β and IL-18 in vitro, and Nlrp3-deficient mice have reduced hypoxic damage." (PMID 35455985, 2022). "In a mouse model of ischemia-reperfusion injury, the inhibition of NLRP3 inflammasomes has been shown to preserve myocardial function." (PMID 34884196, 2021). "Indeed, in mouse ischemia-reperfusion injuries, a subset of inflammatory macrophages highly expressing S100a9 mediate NFkB and NLR family pyrin domain containing 3 (NLRP3) signaling in the early phase and TGFβ in the subsequent reparatory phase." (PMID 39595580, 2024). "Se nanoparticles may alleviate AKI induced by ischemia reperfusion injury by upregulated the (GPx)-1 levels and suppressed NLRP3 inflammasome." (PMID 38486133, 2024). "The aim of this study was to investigate the changes of TLR4/NLRP3 signal during hepatic ischemia-reperfusion injury (HIRI) and to verify whether N-acetyl-L-tryptophan (L-NAT) protected hepatocytes by regulating the activation of TLR4/NLRP3 signal." (PMID 34434653, 2021).
neuroblastoma (15 papers, 2019 to 2026). Neuroblastoma (NB) is the most common solid, extracranial childhood tumor. "The same molecular pathway that must be inhibited to treat neuropathic pain (e.g., NLRP3/caspase‐1/GSDMD) is the one that should be selectively induced to treat neuroblastoma." (PMID 41574659, 2026). "Curcumin (10 μmol L-1) inhibits the activation of the TXNIP/NLRP3 pathway by up-regulating AMPK activity in human neuroblastoma SH-SY5Y cells of human neuroblastoma and reducing ROS produced by endoplasmic reticulum stress." (PMID 37153784, 2023). "It was reported that TRPM2 sustained cell viability, restore mitochondrial function, reduce reactive oxygen species (ROS) in neuroblastoma, and lead to NLRP3 inflammasome activation." (PMID 37608401, 2023). "We found that high expression of NLRP3 was associated with a favorable outcome of neuroblastoma, which corresponds to the NLRP3 reducing the neuroblastoma SH-Y5Y cell line tumorsphere size." (PMID 35664308, 2022). "When co-cultured with the SH-SY5Y neuroblastoma cells under hypoxic conditions, the levels of NLRP3 and cleaved caspase-1 in BV-2 cells were significantly increased, but decreased after TAK-202 treatment." (PMID 33530496, 2021). "This context‐dependent duality presents a fundamental therapeutic challenge: the same molecular pathway (e.g., NLRP3/caspase‐1/GSDMD) that must be inhibited to treat neuropathic pain is the one that should be strategically induced to treat neuroblastoma, necessitating a precision medicine approach." (PMID 41574659, 2026). "Thus, the authors concluded that BPA could induce pyroptosis in neuroblastoma cells through the NLRP3/caspase-1/GSDMD pathway, mediated by ER." (PMID 37855918, 2024). "It has been reported that TNF-α itself has the capability to induce reactive oxygen species-dependent inflammasome activation and IL-1β production in neuroblastoma cells, which could support the idea that NLRP3 is secreted out of the cell upon TNF-α-mediated inflammasome activation." (PMID 32271889, 2020). "Intriguingly, a prediction model with NLRP3/CASP3/IL18/GSDMB was developed, and the high expression of these genes in neuroblastoma correlates with improved survival." (PMID 41574659, 2026). "The mouse neuroblastoma (N2a) and SD rats are treated with LPS and MnCl2 to evaluate the expression of KHSRP and NLRP3." (PMID 36362011, 2022).
oral cancer (15 papers, 2020 to 2026). "Of note, a recent study revealed that soluble La (III) species were found to cause NLRP3 inflammasome activation, which has been proved to be a mechanism for promoting oral cancer." (PMID 35646760, 2022). "In oral cancer, elevated NLRP3 and IL-1β expression frequently correlate with tumor progression, largely driven by mitochondrial dysfunction, impaired autophagy, and alterations in the tumor-associated microbiota." (PMID 41596738, 2026). "Further, the cell line was silenced for inflammasome pathway gene NLRP3 to evaluate its linkage with oral cancer tumorigenesis." (PMID 41410801, 2025). "In this context, TBM-02 can also be used as tool to identify and establish NLRP3 as well as other therapeutic targets of oral cancer." (PMID 41410801, 2025). "Through a critical evaluation of mechanistic and translational findings, we seek to delineate the potential of NLRP3-targeted strategies within oral cancer management and to identify open questions that warrant further investigation." (PMID 41560727, 2025). "This review summarizes mechanistic and clinical knowledge on the biology of NLRP3, highlights its dual role in cancer hallmarks, and discusses the therapeutic promise of targeting the NLRP3-miRNA axis in the management of oral cancer." (PMID 41560727, 2025). "Recently, BAY-117082, as a strong inhibitor of NLRP3 inflammasome, showed significant anti-tumor effects, suggesting its possible use as a promising treatment for oral cancer." (PMID 37345134, 2023). "As NLRP3 is likely to be critically involved in OSCC occurrence, progression, and proliferation, few studies have shed light on possible strategies for oral cancer treatment, regarding the NLRP3-inflammasome." (PMID 35052653, 2022). "Soluble La (III) species have the ability to activate NLRP3 inflammasome, and the latter was regarded as a key mediator of inflammation in promoting the development of oral cancer." (PMID 35646760, 2022). "This study aimed to investigate the effect of BAY-117082, an NLRP3 inflammasome inhibitor, in an in vitro and in vivo xenograft model of oral cancer." (PMID 34681768, 2021). "However, studies are needed to confirm the association between NLRP3 and herpes simplex virus (HSV) subtypes that induce oral cancer." (PMID 41440367, 2025). "Although the pathophysiology of oral cancer remains unclear, in vivo and in vitro studies have demonstrated that aberrant and excessive NLRP3 inflammasome activation significantly contributes to the initiation and progression of oral cancer." (PMID 34681768, 2021). "It has been proven that excessive NLRP3 inflammasome activation and apoptosis alteration may contribute to oral cancer progression." (PMID 34681768, 2021). "Hence, our next aim was to create a NLRP3 knockdown model of early stage oral cancer cell line." (PMID 41410801, 2025). "Consequently, we noticed that inhibition of NE in NETs could significantly abrogate the EMT process, meanwhile promoting the NLRP3 expression of oral cancer cells." (PMID 38697992, 2024). "The NLRP3 inflammasome pathway overactivation could contribute to oral cancer progression." (PMID 37345134, 2023). "However, recent studies have demonstrated that excessive and aberrant NLRP3 inflammasome activation may contribute to oral cancer progression." (PMID 34681768, 2021). "Therefore, based on these results, the use of BAY-117082 could be considered a promising strategy to counteract oral cancer progression, thanks its ability to modulate the NLRP3 inflammasome and apoptosis pathways." (PMID 34681768, 2021). "In an in vitro model employing OSCC cells and an in vivo xenograft model of oral cancer, an NLRP3 inflammasome inhibitor BAY-117082 significantly reduced NLRP3, ASC, caspase-1, IL-1β, and IL-18 expression and a reduction in tumor growth." (PMID 38904007, 2024).
oral cancer (continued). "Recent studies demonstrated that the NLRP3 inflammasome pathway is upregulated in OSCC animal models and OSCC patients, suggesting its involvement in oral cancer pathogenesis." (PMID 34681768, 2021). "Therefore, based on the key roles of the NLRP3 inflammasome and apoptosis pathways in oral carcinogenesis, in this study we decided to evaluate the beneficial effect of BAY-117082 in in vitro and in vivo xenograft models of oral cancer." (PMID 34681768, 2021).
pneumococcal infection (15 papers, 2010 to 2025). Infections with bacteria of the species streptococcus pneumoniae. "NLRP3 protein recognizes pathogen-associated molecular patterns as a part of the innate immune system and provides protection of the human body against Streptococcus pneumonia infection." (PMID 39144184, 2024). "Studies on pneumococcal infections of mouse peritoneal neutrophils indicate that NLRP3 inflammasome is mainly responsible for IL-1β secretion, while the AIM2 and NLRC4 inflammasomes are dispensable in these type of immune cells." (PMID 33424869, 2020). "These microbiocidal activities also typically damage the host; however, an inflammasome-independent activity of NLRP3 was shown to preserve the alveolar epithelial cell integrity during Streptococcus pneumoniae infection in a mouse model." (PMID 33260788, 2020). "NLRP3 plays a role in identifying pneumococcal infection, activating macrophages and has been shown to directly interact with pneumolysin during pneumococcal infection." (PMID 29988379, 2018). "We demonstrate here that NLRP3 protects the alveolar barrier upon pneumococcal infection or PLY challenge." (PMID 27476670, 2016). "In the present study, we employ different in vivo, ex vivo, and in vitro models to examine the effect of NLRP3 on the lung barrier integrity during pneumococcal infection and response to PLY." (PMID 27476670, 2016). "One of the key observations in this study is that NLRP3 is required for protective immunity against pneumococcal infection." (PMID 21085613, 2010). "Moreover, FSTL1 was expressed after Streptococcus pneumoniae infection, positively modulated the NLRP3 (NACHT, LRR, and PYD domain-containing protein 3) inflammasome, and promoted inflammatory injury during infection through the TLR4/NF-κB signaling pathway." (PMID 37322475, 2023). "Although a low level of ROS promotes NLRP3 inflammasome activation, a recent study demonstrated that a high level of ROS generated by Streptococcus pneumonia infection inhibited the NLRP3 inflammasome through the oxidation of the inflammasome components ASC and caspases." (PMID 31979265, 2020). "Additionally, NLRP3 inflammasome-dependent release of IL-1β is critical for neutrophil antibacterial responses to Streptococcus pneumoniae infection in the lungs." (PMID 31586037, 2019).
polycystic ovary syndrome (15 papers, 2019 to 2026). A disorder that manifests as multiple cysts on the ovaries. "Attenuation of hyperandrogenism, apoptosis, oxidative stress and NF-κB/NLRP3 immunoreactivity eliminates renal dysfunction in animals with experimental polycystic ovary syndrome." (PMID 39991152, 2025). "Most importantly, NLRP3 was also suggested to be involved in the pathophysiology of polycystic ovary syndrome (PCOS)." (PMID 34805147, 2021). "Furthermore, enhanced understanding of the contribution and regulation of NLRP3 inflammasomes during ovarian ovulation will be helpful to treat anovulatory infertility, like luteinized unruptured follicle syndrome and polycystic ovary syndrome." (PMID 31750302, 2019). "In polycystic ovary syndrome (PCOS), elevated levels of ROS in ovarian tissue and increased expression of NLRP3 components lead to chronic low-grade inflammation." (PMID 39791737, 2025). "NLRP3-driven inflammation contributes to reproductive pathologies, including endometriosis, polycystic ovary syndrome (PCOS), and RPL." (PMID 40977728, 2025). "Recent studies have demonstrated that ovarian granular cells (OGCs) pyroptosis is present in the ovaries of polycystic ovary syndrome (PCOS) mice and that NLRP3 activation destroys follicular functions." (PMID 37244286, 2023). "Postnatal overfeeding stimulated JNK1 activation independent of hyperandrogenemia; nevertheless, the synergistic effect of both factors triggered NLRP3 activation and increased IL1β expression in the small litter DHT-treated group." (PMID 39268230, 2024). "Furthermore, hyperandrogenemia, one of the main pathophysiological changes that take place in patients with PCOS, results in GC pyroptosis in PCOS patients via the activation of NLRP3 inflammasome, in parallel to previous reports." (PMID 39026050, 2024).